CENPN (centromere protein N)
Diseases named in the same sentence as CENPN in open-access papers (continued):
Sharing a sentence is not in itself a finding about the gene and the disease.
tumor (15 papers, 2019 to 2025). "Using the GEPIA tool to analyze data from HNSCC patients in TCGA database, we found that the CENPN expression level was significantly higher in the tumor group than in the control group." (PMID 40458725, 2025). "We found that all but one showed a very strong straight-line relationship (R-squared ≥ 0.7) between their median expression and the tumour subtypes (RNA level), with the CENPN as the first on the list (R-squared = 0.99)." (PMID 35167614, 2022). "Recent literatures have reported that centromere protein N (CENPN) participates in tumor development." (PMID 34646306, 2021). "The CIBERSORT algorithm was further used to investigate the influence of CENPN on the infiltration of 22 TILs in the tumor microenvironment." (PMID 34646306, 2021). "When the clinical features of CENPN were combined in the analysis, the Wilcoxon rank-sum test revealed that CENPN expression in tumor tissues was dramatically higher than that in normal." (PMID 33987018, 2021). "Functional assays demonstrated that two miRNAs acted as tumor-suppressive miRNAs in BC cells by targeting cell-cycle-related genes (e.g., TRIP13, CCNB1, RAD51, PSPH, CENPN, KPNA2, and MXRA5)." (PMID 39728605, 2024). "However, the specific molecular mechanisms by which CENPN regulates tumor cell invasion and metastasis have not yet been clearly reported." (PMID 40458725, 2025). "However, the relationship between CENPN and tumor chemotherapeutic resistance has not yet been reported." (PMID 37776538, 2024).
cancer (11 papers, 2012 to 2025). A tumor composed of atypical neoplastic, often pleomorphic cells that invade other tissues. "A pan-cancer database of Genotype Tissue Expression (GTEx) and the Cancer Genome Atlas (TCGA) were used to examine the expression of CENPN." (PMID 37697245, 2023). "As a means of assessing the utility of CENPN expression in predicting cancer patient prognosis, we examined the relationship between CENPN expression and DMFS, OS, and RFS in the TCGA cohort." (PMID 37697245, 2023). "In conclusion, CENPN encourages biological processes that lead to cancer, such as the migration and proliferation of BC cells." (PMID 37697245, 2023). "The human CD44/MYC-high cluster expressed CENPK and CENPN, which regulate the cell cycle and cell division in cancer." (PMID 35611554, 2022). "Recently, the relevance of CENPN to the occurrence and progression of different cancers has been proposed." (PMID 34646306, 2021). "The modules significantly contained the nodes (i.e., CENPA, CENPN, and CENPH) which are associated with different cancers and disease progression." (PMID 30658502, 2019). "Cenpp, as well as CenpN/F/H/J/I/C1/T/K/M/E/Q/A/L, are all co-expressed significantly with the cancer seed list and are part of the Cenp-A NAC complex." (PMID 23039964, 2012). "CENPN is closely related to the occurrence and development of many kinds of cancer." (PMID 33987018, 2021).
CENPN also shares sentences with these, for which no sentence is quoted: melanoma (2 papers); adenocarcinoma (1); cervical squamous cell carcinoma (1); esophageal cancer (1); infection (1); lung carcinoma (1); lymph node metastasis (1); malignant glioma (1); oral cancer (1); osteosarcoma (1); prostate tumor (1); psoriasis (1); Sepsis (1); triple-negative breast carcinoma (1).